NSDHL (NAD(P) dependent 3-beta-hydroxysteroid dehydrogenase NSDHL)
Diseases named in the same sentence as NSDHL in open-access papers (continued):
Sharing a sentence is not in itself a finding about the gene and the disease.
tumor (13 papers, 2020 to 2025). "The association between the dysregulated CHOL biosynthesis and tumor aggressiveness was confirmed by the inverse association between the tumor expression level of HMGCR or NSDHL and the patient’s relapse-free survival." (PMID 38254664, 2024). "The study also found that the expression level of HMGCS1, HMGCR, SQLE, and NSDHL progressively increased with tumor grade and correlated positively with the expression of MKI67, the gene coding for the proliferation marker Ki67." (PMID 38254664, 2024). "Our findings suggest that NSDHL regulates the BCSC/tumor-initiating cell population in MCF-7 spheroids and xenograft tumors." (PMID 39516821, 2024). "BSCS subpopulations with the CD44+/CD24- phenotype or high ALDH activity were analyzed to verify the role of NSDHL in maintaining the BCSC population within tumor tissues." (PMID 39516821, 2024). "Among the neoantigens are well-known genes associated with tumor progression and metastases, such as HAUS3, NSDHL, MAGEA10, FNDC3B, TEAD1, DHX33, PGM5, and MLL2." (PMID 36607962, 2023). "For example, SC4MOL and NSDHL inactivation sensitizes tumor cells to EGFR inhibitors, and DHCR24 heterozygous knockout in mice reduces cholesterol levels without causing health problems." (PMID 35386193, 2022). "NSDHL knockdown led to significantly decreased tumor growth and lung metastasis in the MDA-MB-231 xenograft model (p < 0.01)." (PMID 32366230, 2020). "As shown in the gross images of the tumors excised at the end of 44 days, tumor wet weights were significantly lower in the NSDHL knockdown group (n = 5) than in the control group (n = 5)." (PMID 32366230, 2020). "More intriguingly, knockdown of cholesterol biosynthesis pathway gene NSDHL, markedly sensitizes tumor cells to epithelial growth factor receptor (EGFR) inhibitors." (PMID 32366230, 2020). "Primary tumor volumes measured weekly were significantly lower in the NSDHL knockdown group (n = 5) than in the control group (n = 5)." (PMID 32366230, 2020). "The representative IHC for NSDHL showed strong staining in the control tumor and overall weak staining in the NSDHL-knockdown tumor." (PMID 32366230, 2020). "We aimed to investigate whether NSDHL plays a role in maintaining BCSCs and to elucidate the molecular mechanism by which NSDHL regulates BCSCs in ER-positive MCF-7 tumor spheroids and orthotopic tumor xenograft models." (PMID 39516821, 2024). "However, little research has been conducted on the biological involvement of NSDHL in BCSCs maintenance and tumor-initiating capacity." (PMID 39516821, 2024). "Therefore, in this study, we investigated the response of breast cancer cells and tumor progression to NSDHL knockdown in breast cancer cells and in xenograft tumor mice." (PMID 32366230, 2020). "Our data showed that both ENO1, PFKFB3, NSDHL and SQLE have high expression levels in clinical HNSCC samples, and all of them presented higher expression in patient with recurrence tumor." (PMID 36841765, 2023). "As hypothesized, NSDHL knockdown inhibited spheroid formation in MCF-7 cells grown on polymer-X-coated ultra-low attachment plates and delayed tumor initiation in a mouse tumor model by injecting MCF-7 spheroids." (PMID 39516821, 2024). "Furthermore, we observed that ENO1, PFKFB3, NSDHL and SQLE were highly expressed in recurrent HNSCC tumor compared with first diagnosed HNSCC patients surviving at least 5 years." (PMID 36841765, 2023). "In the Th17 lineage, RORC (receptor) is upregulated on the tumor infiltrating CD4+ T-cells and its ligands (CYP51A1, FDFT1, HSD17B7, LBR, TM7SF2, MSMO1, NSDHL) are also upregulated on the tumor cells, implying GBM expresses ligands that induces Th17 phenotype in tumor infiltrating helper T-cell." (PMID 34012510, 2021).
tumor (continued). "Analysis based on the Spearman correlation coefficient indicated a very weak positive correlation between NSDHL and SOX2 expression in patient tumor tissues (n = 998, r = 0.089, P = 0.005), whereas a negative correlation was found between NSDHL and NANOG expression (n = 998, r = -0.038, P = 0.24)." (PMID 39516821, 2024).
cancer (11 papers, 2017 to 2025). A tumor composed of atypical neoplastic, often pleomorphic cells that invade other tissues. "While NSDHL is implicated in cancer development in humans, research on this gene in livestock and poultry remains limited." (PMID 39765715, 2024). "NSDHL is also a cholesterol synthesis, which related to cancer growth and the signaling of proto-oncogenes." (PMID 36841765, 2023). "NSDHL involved in the endogenous pathway of cholesterol biosynthesis has been suggested as a critical target for cancer therapy." (PMID 32366230, 2020). "Interestingly, the knock-down of another gene in the same community, the NAD(P)H Steroid Dehydrogenase-Like (NSDHL), conferred higher survival and had a positive effect on cancer cells." (PMID 38927057, 2024). "Recently, NSDHL was identified as a regulator of oncogenesis in various cancer models." (PMID 39516821, 2024). "The results showed that ENO1, PFKFB3, NSDHL and SQLE were primarily detected in the in the cytoplasm of cancer cells in HNSCC tissues and the expression of these protein in recurrent HNSCC was significantly higher than that in normal tissues." (PMID 36841765, 2023). "Mechanistically, NSDHL knockdown impaired the cancer stemness characteristics of BCSCs by suppressing TGF-β signaling, which in turn decreased the secretion of TGF-β 1 and TGF-β3, inactivated Smad2 and Smad3, and downregulated the expression of SOX2 and NANOG, key regulators of cancer stemness." (PMID 39516821, 2024). "The top five genes were HMGCR, LDL1 (low‐density lipoprotein 1), ACAT2 (acetyl‐CoA acetyltransferase 2), NSDHL (NAD[P] dependent steroid dehydrogenase‐like), and LDLR1 (low‐density lipoprotein receptor 1), all of which were positively correlated with HMGCS1 in most cancer types." (PMID 34549901, 2022).
NSDHL also shares sentences with these, for which no sentence is quoted: Limb Defects (2 papers); Anxiety (1); colon cancer (1); Cornification Disorder (1); hepatocellular carcinoma (1); Hypercholesterolemia (1); metabolic disease (1); mevalonic aciduria (1).